RBP4 (retinol binding protein 4)
Diseases named in the same sentence as RBP4 in open-access papers (continued):
Sharing a sentence is not in itself a finding about the gene and the disease.
Insulin resistance (continued). "Insulin resistance and obesity is influenced by the retinol binding protein 4 (RBP4) adipokine." (PMID 25479076, 2014). "Recent studies have suggested that RBP4 may produce a molecular connection between obesity and insulin resistance." (PMID 24475021, 2014). "RBP-4 increases insulin resistance by suppressing peripheral expression of GLUT4 transporters." (PMID 26464853, 2014). "RBP4 has been proposed recently as an adipokine that may contribute to insulin resistance in muscle and liver, both in mice and humans." (PMID 24665145, 2014). "Of these, two (RBP4 and Fetuin-A) were previously reported in the context of insulin resistance." (PMID 24800810, 2014). "Thus, the relationship between adipose RBP4 expression, circulating levels of RBP4, obesity and insulin resistance in humans needs to be evaluated in future studies." (PMID 24733068, 2014). "Along with markers of obesity and insulin resistance, RBP4 is correlated with inflammatory factors." (PMID 24733068, 2014). "Recent studies have suggested that retinol binding protein 4 (RBP4), an adipocytokine related to insulin resistance (IR), may play an important role in the development of atherosclerosis and cardiovascular diseases (CVD)." (PMID 24604418, 2014). "The correlations of visfatin/Nampt, vaspin, and RBP-4 with insulin resistance are tissue dependent." (PMID 24367155, 2013). "Thus, in order to gain further insight into the relation between RBP4, insulin resistance and lipid metabolism, we studied a large cohort of obese subjects with different degrees of insulin resistance." (PMID 24223837, 2013). "Interestingly, pharmacologic administration of RBP4 and transgenic overexpression of RBP4 both induce insulin resistance in mice, while genetic deletion of RBP4 enhances insulin sensitivity." (PMID 23840311, 2013). "RBP4 is elevated in T2DM and is linked to insulin resistance." (PMID 24099047, 2013). "In rodent models, circulating RBP4 correlates positively with insulin resistance and RBP4 directly induces insulin resistance presumably by increased expression of the hepatic gluconeogenic enzyme phosphoenolpyruvate carboxykinase and impaired skeletal muscle insulin signaling." (PMID 23781325, 2013). "In addition, AECOPD patients reach an advanced state of inflammation where RBP4 is negligible in insulin resistance." (PMID 24099047, 2013). "More recently, plasma RBP4 has been identified as an important signal of insulin resistance." (PMID 23840311, 2013). "Visfatin/Nampt, vaspin, and retinol binding protein-4 (RBP-4) are novel adipokines and may play important roles in insulin resistance development." (PMID 24367155, 2013). "Retinol binding protein 4 (RBP4) is an adipokine that may contribute to the development of insulin resistance." (PMID 24223837, 2013). "However, we did observe a significant increase in serum RBP4 levels in patients with high levels of triglycerides independently of their degree of insulin resistance and gender." (PMID 24223837, 2013). "In conclusion, these clinical studies do not support a causal association between insulin resistance and RBP4 serum levels in human subjects." (PMID 23781325, 2013). "Some researchers explored the relationship of RBP4 and insulin resistance." (PMID 24160775, 2013). "In addition, growing evidence suggests that RBP4 plays a role in lipid metabolism to an even greater extent than insulin resistance." (PMID 24223837, 2013). "RBP4 was described as a potential mediator of insulin resistance in these mice." (PMID 23431266, 2013). "Studies have reported strong evidence that suggests YKL-40, α-HB, soluble CD36, leptin, resistin, IL-18, RBP4, and chemerin could be new biomarkers for the pathogenesis of insulin resistance and endothelial dysfunction in T2DM patients." (PMID 24282409, 2013). "However, correlations between RBP4 and vascular endothelium, oxidative stress, low-grade inflammation related to insulin resistance, and diabetic complications are still unclear." (PMID 24282409, 2013).
Insulin resistance (continued). "RBP4 was identified as a signal transferring protein for insulin resistance." (PMID 23671852, 2013). "Most but not all of the findings suggest that plasma RBP-4 levels are positively associated with body fat percentage and insulin resistance." (PMID 23772224, 2013). "However, it is still unclear why RBP4 correlated only with WC instead of VFA which is closely related to insulin resistance." (PMID 23671852, 2013). "The objectives of this study were to measure visfatin/Nampt, vaspin, and RBP-4 concentrations in blood, liver, muscle, subcutaneous, omental, and mesenteric adipose tissues in morbidly obese subjects and investigate their relationship to insulin resistance." (PMID 24367155, 2013). "The association between RBP4 and CIMT, a measure of systemic atherosclerosis, has been investigated in only a few studies, and as with relationships between RBP4 levels and obesity, insulin resistance, and other CVD risk markers, results conflict." (PMID 22587616, 2012). "PPARγ and RBP4 are known to regulate lipid and glucose metabolism and insulin resistance." (PMID 23145084, 2012). "RBP4 is known as a key regulator in obesity-related insulin resistance and type 2 DM." (PMID 22778782, 2012). "These bioactive molecules, including leptin, adiponectin, visfatin, omentin, tumor necrosis factor-α (TNF-α), resistin, retinol-binding protein 4 (RBP4) and many others influence metabolic processes such as food intake, glucose- and lipid-metabolism, inflammation and insulin resistance." (PMID 22389718, 2012). "There is increasing evidence suggesting that RBP-4 may be an important link between increases of visceral adiposity and insulin resistance." (PMID 22828276, 2012). "In acute critically ill patients, serum RBP-4 concentrations were significantly reduced and showed a strong association with hepatic dysfunction, insulin resistance, and acute mortality, possibly as a negative acute phase reactant." (PMID 22272381, 2012). "Therefore, we were unable to calculate insulin resistance via the homeostasis model assessment (HOMA-IR), and a bias towards the null was introduced for associations between RBP4 and lipids and glucose." (PMID 22587616, 2012). "Recently, two mechanisms by which RBP4 induces insulin resistance have been proposed, suggesting that both apo- and holo-RBP4 could participate in tissue insulin resistance." (PMID 23201837, 2012). "Since high levels of ROH and RBP4 have been associated with an increased risk of CVD and insulin resistance, future research should focus on these associations in donors especially with regard to the baseline risk for CVD and insulin resistance as well as on potential underlying mechanisms." (PMID 22151790, 2011). "However, serum RBP4 levels correlated with endogenous insulin secretion (C-peptide) and insulin resistance (HOMA index)." (PMID 20932285, 2010). "The correlation with insulin resistance and the relation with the acute mortality collectively suggest that RBP4 may have implications for the pathogenesis of critical illness and could serve a novel biomarker for ICU patients." (PMID 20932285, 2010). "But neither functional nor genetic studies have been carried out to identify how STRA6 may play a role in imparting the effect of RBP4 on muscle and liver insulin resistance and subsequently type 2 diabetes." (PMID 20625434, 2010). "Therefore, RBP4 and resistin levels appear to better predict obesity and insulin resistance than leptin in our model." (PMID 20633301, 2010). "Among the biomarkers that we measured, RBP4 and resistin have previously been shown to be necessary and sufficient to induce insulin resistance and genetic disruption or impaired leptin signaling has been shown to lead to obesity and insulin resistance." (PMID 20633301, 2010).
Insulin resistance (continued). "Although serum RBP4 did not correlate with serum glucose on admission to the ICU, serum RBP4 correlated with the C-peptide (r = 0.305, P = 0.001), with the insulin resistance as calculated by the HOMA index (HOMA-IR; r = 0.248, P = 0.009; HOMA-S, r = -0.248, P = 0.009)." (PMID 20932285, 2010). "Our results further indicate that the elevated serum RBP4 might be involved in the development of insulin resistance in ICU patients." (PMID 20932285, 2010). "However, the role of RBP4 in the development of insulin resistance and tumorigenesis is less significant in patients with lower BMI, which may be attributable to adipose tissue dysfunction in obesity." (PMID 41007818, 2025). "RBP4 binds to toll-like receptor 4 on muscle cells, triggering nuclear factor kappa-light-chain-enhancer of activated B cells (NF-κB) and mitogen-activated protein kinases (MAPKs) pathways, promoting inflammatory gene transcription and contributing to insulin resistance." (PMID 40276651, 2025). "Additionally, increased levels of retinol-binding protein 4 (RBP4) associated with hyperuricemia (HUA) can specifically inhibit the IRS/phosphatidylinositol 3-kinase (PI3K)/Akt pathway in adipocytes, further exacerbating insulin resistance." (PMID 41301787, 2025). "Therefore, reducing the circulating RBP4 concentration might be a potential way to improve insulin resistance and T2DM." (PMID 38520616, 2024). "Elevated levels of RBP4 attract macrophages to adipose tissue and promote local inflammation by causing macrophages to secrete pro-inflammatory cytokines: nuclear factor κ-B (NFκB), c-Jun N-terminal kinases (JNK), and interleukin 1β, leading to insulin resistance." (PMID 38966226, 2024). "In addition to the small sample size and cross-sectional design, which are prone to research bias, several other factors may explain the discontent relationship between RBP4 levels and insulin resistance." (PMID 38520616, 2024). "The different sources of RBP4 may determine its influence on insulin resistance." (PMID 38520616, 2024). "Furthermore, they exhibited significantly elevated levels of serum leptin and RBP-4, along with decreased levels of serum adiponectin, which may indicate a potential link to insulin resistance." (PMID 37854195, 2023). "RBP4, mainly secreted by the liver and adipocytes, is a transporter of vitamin A and it is involved in various pathophysiological processes, such as obesity, insulin resistance and cardiovascular diseases, demonstrating a strong association of this mirtron to inflammatory-related processes." (PMID 37141193, 2023). "Indeed, high levels of RBP4 may induce insulin resistance via its effects on glucose clearance because of the potentially altered adipose tissue regulation." (PMID 36835525, 2023). "Finally, we wanted to validate that the observed changes in serum RBP-4 levels following chiglitazar 32 mg, chiglitazar 48 mg, and sitagliptin 100 mg treatment could contribute to the improved insulin resistance observed in these patients." (PMID 35547000, 2022). "In addition, it is also important to note that insulin resistance marked by the increased levels of RBP4 may also be a result of iron overload, hemolytic anemia and thrombosis, as these were all suggested in our study." (PMID 35977993, 2022). "Retinol binding protein 4 (RBP4), mainly secreted by the liver and adipocytes, is a transporter of vitamin A. RBP4 has been shown to be involved in several pathophysiological processes, such as polycystic ovary syndrome (PCOS), obesity, insulin resistance, and cardiovascular risk." (PMID 34068244, 2021). "In a large study, which included subjects with various cardiometabolic risk factors, urinary RBP-4, which might be the consequence of increased circulating RBP-4, was positively associated with brachial–ankle PWV, insulin resistance, microalbuminuria, and inflammation." (PMID 34202323, 2021).
Insulin resistance (continued). "Hence, retinol-binding protein-4 may serve as a valuable biological indicator to depict insulin resistance and the severity of coronary artery disease." (PMID 34571734, 2021). "It was therefore suggested to connect obesity-associated comorbidities, especially insulin resistance (IR), and certain components of the metabolic syndrome such as nonalcoholic fatty liver disease (NAFLD), in either retinol-dependent or retinol-independent way, with RBP4." (PMID 33135589, 2020). "Thus, the current study aimed to investigate the effect of RBP4 levels both in the first trimester and second trimester on insulin resistance and GDM in a prospective cohort of Chinese women, after adjustment for potential confounders including diet and physical activity." (PMID 31921323, 2020). "However, recent studies revealed that RBP4 could be a new adipokine with potential involvement in the pathogenesis of insulin resistance and type 2 diabetes mellitus (DM)." (PMID 31921323, 2020). "Also, RBP4 is an important link between obesity and insulin resistance." (PMID 26842399, 2016). "Although RBP-4 and resistin have been associated with obesity and insulin resistance, and may be altered in pregnancy, they do not appear to be predictive of GDM development." (PMID 26110385, 2015). "Even under these conditions, RBP4 can regulate TG metabolism especially at the remnant level, but visceral fat accumulation and factors associated with insulin resistance may not be the main pathway for RBP4 to regulate TG metabolism." (PMID 23671852, 2013). "However, it is a matter of controversy whether RBP4 levels in obesity are determined by insulin resistance." (PMID 24223837, 2013). "Serum RBP4 levels were increased and correlated with subclinical inflammation in childhood obesity, while in adipose tissue, mRNA level of RBP4 was positively linked to inflammatory markers rather than insulin resistance." (PMID 23799122, 2013). "Therefore, we focused mainly on its relationship with insulin-resistant states in this study, although some reports have shown that RBP4 could play a more important role in lipid metabolism than in insulin resistance." (PMID 23671852, 2013). "Therefore, increased ROH and RBP4 serum concentrations in donors may increase their risk of CVD and insulin resistance post-nephrectomy." (PMID 22151790, 2011). "Our reported increase in plasma retinol in this model of type 2 diabetes is in contrast to the type 1 diabetes data, but is consistent with previous reports of diabetes-induced increases in RBP4, a retinol-binding protein which may be a biomarker of type 2 diabetes and insulin resistance." (PMID 20559430, 2010). "The triad of GLUT4-RBP4-STRA6 may play an important role in the pathogenesis of type 2 diabetes, wherein the adipocyte specific down regulation of GLUT4 leads to an increased expression of RBP4 and this increase in RBP4 expression leads to insulin resistance via STRA6." (PMID 20625434, 2010). "We hypothesized that the insulin resistance that is present in critical illness would affect circulating adiponectin, RBP4, and leptin levels and that the improved insulin sensitivity that we observed in intensive insulin therapy (IIT) patients would change the adipokine levels." (PMID 19589139, 2009). "Specifically, iron accumulation enhances the expression of resistin and retinol-binding protein 4 (RBP-4), while it inhibits the expression of insulin sensitizing leptin, resulting in insulin resistance." (PMID 39941760, 2025). "In this study, we analysed serum levels of RBP4, LCN2 and hsCRP in patients diagnosed with IFG, IGTand T2DM and a control group and their relationships with other variables of insulin resistance, carbohydrate metabolism and homeostasis." (PMID 40951890, 2025). "RBP4 and LCN2 correlate with insulin resistance and cardiovascular disease burden, and elevated circulating levels predict adverse outcomes and event severity in CAD populations." (PMID 41303567, 2025).
Insulin resistance (continued). "Pro-inflammatory adipokines such as RBP4 and LCN2 contribute to insulin resistance, oxidative stress and endothelial dysfunction." (PMID 41303567, 2025). "Retinol binding protein 4 (RBP4), as an adipokine, has been known to be related to insulin resistance and, probably, induce adipose tissue inflammation." (PMID 40641114, 2025). "In summary, adipokine markers contributing to insulin resistance, such as leptin, chemerin, FABP4, and RBP4, are typically elevated in GDM, whereas those contributing to insulin sensitivity, like adiponectin, are reduced in GDM." (PMID 39519218, 2024). "In this review, we update and summarize recent studies focused on the relationship between RBP4 and T2DM and its role in insulin resistance and pancreatic β-cell function to clarify the existing controversy and provide evidence for future studies." (PMID 38520616, 2024). "SIT treatment was associated with increased expression of insulin receptor one and decreased expression of makers for insulin resistance, including phospho-PKC- alpha, RBP-4, SIRT1, and PI3K (p<0.05)." (PMID 39074126, 2024). "The binding of holo-RBP4 to STRA6, the cell surface receptor of RBP4, directly inhibits insulin signaling by activating the JAK2/STAT5/SOCS3 pathway, leading to insulin resistance." (PMID 38520616, 2024). "In patients with insulin resistance, the adipokines resistin, leptin, PAI-1, and retinol binding protein 4 (RBP4) can dysregulate the insulin receptor substrate-1 (IRS-1) level in megakaryocytes, thus disrupting insulin signaling in platelets." (PMID 38672744, 2024). "Plasminogen activator inhibitor (PAI)-1, Adiponectin, retinol-binding protein-4 (RBP4), chemerin, and adipocyte fatty-acid-binding protein (A-FABP) have been suggested as potential biomarkers for insulin resistance." (PMID 39518747, 2024). "Several adipokines/cytokines such as leptin, resistin, retinol-binding protein 4 (RBP4), angiopoietin-like protein 2, IL-6 and MCP-1 promote the atherosclerotic process by inducing inflammation, endothelial dysfunction and insulin resistance." (PMID 39867890, 2024). "Retinol binding protein 4 (RBP4), as a novel adipokine, has been proven to be highly related to insulin resistance, obesity, diabetes, hypertension, hyperuricemia and other metabolic diseases, which are all risk factors for chronic kidney disease (CKD)." (PMID 39698033, 2024). "Researchers have conducted a series of experiments to understand the interplay between RBP4 and T2DM, including its role in insulin resistance and pancreatic β-cell function." (PMID 38520616, 2024). "Despite these inconsistencies, the intervention study demonstrated that exercise decreased RBP4 levels in individuals with insulin resistance and that there was an inverse relationship between GLUT4 protein levels and serum RBP4 levels in adipose tissue." (PMID 38520616, 2024). "We evaluated the efficacy and significant changes in the levels of retinol-binding protein 4 (RBP-4) and insulin resistance in patients with type 2 diabetes mellitus (T2DM) treated with chiglitazar versus sitagliptin." (PMID 35547000, 2022). "Finally, due to its ability to decrease RBP4 serum levels and, consequentially, to modulate insulin resistance and glucose intolerance, fenretinide could have a positive impact on neurological diseases in which glucose metabolic dysfunctions represent a risk factor." (PMID 35806431, 2022). "Retinol-Binding Protein 4 (RBP4) activates pro-inflammatory pathways and increases insulin resistance." (PMID 35740032, 2022). "Retinol-binding protein 4 (RBP4), an adipokine responsible for obesity-induced insulin resistance, has been identified as one of the reliable biomarkers for the early diagnosis of T2DM." (PMID 36551028, 2022). "Mice overexpressing human or murine RBP4 in adipocytes and fed with HFD are more prone to develop obesity, insulin resistance and hepatic steatosis than wildtype littermates." (PMID 34638803, 2021).